HYOU1 (hypoxia up-regulated 1)
Diseases named in the same sentence as HYOU1 in open-access papers (continued):
Sharing a sentence is not in itself a finding about the gene and the disease.
tumor (continued). "Hypoxia up-regulated 1 (HYOU1), a member heat shock protein 70 family, maintains endoplasmic reticulum (ER) homeostasis under hypoxia conditions while promotes growth, metastasis and invasion of tumor cells by activating the PI3K/Akt signaling pathway." (PMID 38650282, 2021). "HYOU1 is a chaperone protein located in the ER and serves not only as a potential therapeutic target for cancer but also as an immunostimulatory adjuvant, owing to its anti-tumour immune response." (PMID 36291587, 2022).
cancer (32 papers, 2013 to 2025). A tumor composed of atypical neoplastic, often pleomorphic cells that invade other tissues. "SOD3, HYOU1, and PPFIA2 show the strongest association with both racial differences and survival, indicating a potential role in racial disparities in cancer outcomes." (PMID 40558258, 2025). "The second μ-17-specific cancer-associated module comprises endoplasmic reticulum (ER) molecular chaperones (PDIA4, PDIA6, GANAB) and heat shock proteins (HYOU1, HSPA5, DNAJB11)." (PMID 41373892, 2025). "The monoamine oxidase B (MAOB) and hypoxia upregulated 1 (HYOU1) have been reported to be upregulated in hepatotoxicity as well as in various cancers." (PMID 38992651, 2024). "Apart from its significant protective function in the formation and progression of tumors, HYOU1 can be a promising target for treating cancer." (PMID 38609844, 2024). "HYOU1 is overexpressed under hypoxic conditions and contributes to the movement and metastasis of cancer cells in various human cancers." (PMID 39772207, 2024). "The results showed that the unfolded proteins HSPA5, HYOU1, and PDIA4 were associated with survivability in cancer, and HSPA5 was positively and significantly correlated with CD47, and induced by CD47 in OSCC cells lines." (PMID 35678681, 2022). "We focused on EPRS and HYOU1 due to both proteins being in the top 10% features that distinguish malignant from control tissue and due to their positive staining based on the Cancer Protein Atlas." (PMID 27799870, 2016). "Furthermore, it has been demonstrated that HYOU1 is related to various pathologic situations, such as ischemic brain, malignant tumors." (PMID 33670352, 2021). "However, molecular mechanism underlying oncogenic function of HYOU1 in cancer progression is not fully clarified." (PMID 33792181, 2021). "To further explore the role of CD47, HSPA5, HYOU1, and PDIA4 genes in cancer, we used the human protein atlas (HPA) database to analyze the expression of these target genes in cancer and their impact on the ability of cells to survive." (PMID 35678681, 2022). "The results found that HSPA5, HYOU1, and PDIA4 were involved in the IPA network and when highly expressed, mediated the survivability of cancer." (PMID 35678681, 2022).
infection (4 papers, 2015 to 2025). The state of being infected such as from the introduction of a foreign agent such as serum, vaccine, antigenic substance or organism. "Mutations in the HYOU1 gene cause converging defects, including impaired B-cell maturation, reduced T-cell activation under stress, increased susceptibility of immune cell death during infection, and defective antigen presentation." (PMID 41583281, 2025). "Other host proteins that were not recurring across the 15 interactomes but common in other interactomes such as HYOU1, PDIA3, HSPA9, CTSS, etc., have been already also found deregulated upon pathogenic infection." (PMID 30815000, 2019). "The marginal suppression of HYOU1 was observed after an infection with H37Ra of THP-1 cell." (PMID 25785198, 2015). "Our results also indicated the downregulation of certain proteins after infection with H37Ra such as inactive rhomboid protein 2 (RHBDF2), canopy-2 (CNPY2), hypoxia upregulated protein 1 (HYOU1), and protein transport protein sec23A (SC23A)." (PMID 25785198, 2015).
adenocarcinoma (1 paper, 2016). A common cancer characterized by the presence of malignant glandular cells. "HYOU1 and NANS were both positively correlated with adenocarcinoma-associated increases in EPRS, which was also positively associated with LRPPRC and COPG1." (PMID 27799870, 2016). "EPRS and HYOU1 immunostaining were elevated in adenocarcinoma relative to control tissue." (PMID 27799870, 2016). "HYOU1 was expressed in all 40 (100%) cases of adenocarcinoma." (PMID 27799870, 2016). "The staining of HYOU1 in adenocarcinoma cells was localized in the cytoplasm." (PMID 27799870, 2016). "Increased protein levels of HYOU1, EPRS and LASP1 in NSCLC adenocarcinoma was independently validated by tissue microarray immunohistochemistry." (PMID 27799870, 2016). "Consistent with our proteomic data, mRNA expression of APEX1, HYOU1, PDIA4, NANS, LRPPRC, EPRS and COPG1 were significantly (Mann–Whitney U < 0.05) higher in adenocarcinoma compared to control whereas mRNA abundance of HBG1, HBG2, HBD, and PTRF were significantly (Mann–Whitney U < 0.05) lower." (PMID 27799870, 2016). "Three top candidate proteins, EPRS, HYOU1 and LASP1 from the discovery study were independently validated with a tissue microarray containing 40 pairs of malignant and non-malignant tissues from patients with early stage NSCLC adenocarcinoma." (PMID 27799870, 2016).
neurological disorders (1 paper, 2025). "Additionally, the ERS-related proteins were downregulated following anti-TNF-α and anti-IL-1β treatment, including those implicated in neurological disorders such as HYOU1, PDIA4, and PDIA3." (PMID 40338234, 2025).
HYOU1 also shares sentences with these, for which no sentence is quoted: prostate carcinoma (4 papers); cervical carcinoma (3); lung fibrosis (2); steatosis (2); acute kidney injury (1); Ataxia (1); bladder cancer (1); brain injury (1); cardiovascular disease (1); cerebellar ataxia (1); Cerebral ischemia (1); cholestasis (1); epileptic seizures (1); glioblastoma (1); goiter (1); hypothyroidism (1); IgA nephropathy (1); Impaired glucose tolerance (1); ischemia (1); kidney failure (1); kidney injury (1); liver cancer (1); lymph node metastases (1); macular degeneration (1); metastatic cancers (1); metastatic melanoma (1); minimal change disease (1); myocardial ischemia (1); nephrotic syndrome (1); non-small cell lung carcinoma (1).
A further 19 diseases each share a sentence with HYOU1 in 1 paper.